CCL2 (C-C motif chemokine ligand 2)
Diseases named in the same sentence as CCL2 in open-access papers (continued):
Sharing a sentence is not in itself a finding about the gene and the disease.
Obesity (continued). "In agreement with our results, it has been shown that obesity promotes breast cancer by CCL2-mediated macrophage recruitment." (PMID 25599228, 2015). "Using the mouse model of diet-induced obesity, it was demonstrated that targeted deletion of the chemokine Ccl2 or its receptor Ccr2 decreased inflammatory ATM content and adipose tissue inflammation." (PMID 24741577, 2014). "A higher production of CCL2 is not only a consequence of obesity but is most likely an exacerbating factor of diet-induced alterations." (PMID 24453432, 2013). "It remains to be seen if CCL2 can predict future metabolic outcomes including obesity, dyslipidemia and dysglycemia." (PMID 23557387, 2013). "Our data indicate that besides CCL2 and CCL5, numerous other chemokines such as CCL19 are expressed by adipocytes under obesity-associated chronic inflammation." (PMID 23824685, 2013). "Other cells are capable of secreting CCL2 in obesity including hepatocytes, skeletal muscle cells, monocytes, vascular smooth muscle and endothelial cells." (PMID 23557387, 2013). "This is a strength in our study, as it takes out insulin resistance as a factor associated with obesity-related inflammation, and isolates the effect of obesity on CCL2 levels." (PMID 23557387, 2013). "The roles of CCL2 in the aetiology of obesity and diabetes, the regulatory mechanisms, and the effect of therapies that inhibit CCL2 production have been recently reviewed." (PMID 24453432, 2013). "Intriguingly, MCP-1 (also known as CCL2), a representative CC chemokine, was found to be remarkably increased in adipose tissue in obesity." (PMID 23964268, 2013). "Biomarkers of inflammation, such as TNF-α, interleukin (IL)-6, monocyte chemoattractant protein-1 (MCP-1, CCL2), and C-reactive protein, are increased in obesity, associated with insulin resistance, and predict the development of type 2 diabetes." (PMID 21589925, 2011). "Both the adipose tissue expression and circulating concentrations of CCL2 increase in obesity and decrease following treatment with thiazolidinediones." (PMID 20936118, 2010). "Therefore, this study clarifies the relationship between obesity and cancer, highlighting CCL2 as a promising therapeutic target for cancer patients who are obese." (PMID 41160815, 2026). "When comparing the average cytokine levels among the groups, we found that the obesity class II‐III group showed a significantly higher expression of CCL2/MCP‐1 and TNF‐α, despite having a considerably lower cell count compared to the normal weight/overweight group." (PMID 40518865, 2025). "This study was a secondary analysis of a single-arm weight loss clinical trial for adults with obesity, which aimed to investigate the effects of ADF-LC on circulating immune response biomarkers that are modulated by obesity including PD-L1, CCL2, CCL4, IL-8, IL-1ra, IFNγ, CD40-L, and IP-10." (PMID 40145019, 2025). "CCL2, a member of the CC chemokine family, is a key factor in obesity-induced inflammation, as it attracts CCR2-expressing monocytes and favors their differentiation into M1 macrophages, which promote adipogenesis and increase the accumulation of adipose tissue." (PMID 39457105, 2024). "The real association between the CCL2, OAS1, and DPP9 variants and the presence of the severe COVID-19 phenotype was examined using multivariable logistic regression analysis to control the influence of age, sex, obesity, and comorbidities." (PMID 38694517, 2024). "Plasma TNFα and CCL2 levels were significantly elevated 6 weeks PS1 in Nx mice compared to sham mice, but remained in a low physiological range as observed in obesity-associated low-grade systemic inflammation." (PMID 38509307, 2024). "Chemokines CCL2 and CCL5 have been associated with elevated levels in adipose tissue in obesity." (PMID 39334887, 2024).
Obesity (continued). "Together with the observation that re-expression of CKB attenuates CCL2 production, our data in vitro and in vivo suggest that restoration of creatine metabolism might mitigate tissue inflammation in obesity and insulin resistance." (PMID 39675471, 2024). "Using a T2DM and a control cohort from the Asir region of Saudia Arabia, we looked into the association between the pro-inflammatory chemokines CCL1, CCL2, CCL4, and CCL5 and the etiopathogenesis of T2DM in subjects with different degrees of obesity, BMI, and HbA1c." (PMID 39063997, 2024). "Moreover, HFD-induced obesity promoted KLF7/CCL2 expression in BMA and PCa cell growth in the bone marrow cavity of the mice." (PMID 38221626, 2024). "For example, monocyte chemoattractant protein (MCP-1 or CCL2), a chemokine produced in both adipocytes and the stromal vascular (SV) portion of adipose tissue, is significantly elevated in both blood and adipose tissue in obesity." (PMID 37153549, 2023). "In some cases, inflammatory factors such as TNF-α in the peripheral circulation of individuals with obesity stimulate microglia to produce MCP-1/C-C motif chemokine 2 (CCL2) and brain monocytes and activate vagal afferent neurons to induce central inflammation." (PMID 37249983, 2023). "Moreover, the induction of adiponectin by means of the PPARγ agonism suppresses the elevation in CCL2 levels by blocking TNF- α signaling, thereby attenuating obesity-associated PPAT inflammation." (PMID 35406450, 2022). "Elevated circulating levels of CCL2 following treatment could potentially be a significant problem in breast cancer patients with obesity." (PMID 35435599, 2022). "Our findings suggested that BBR ameliorates obesity-induced inflammation by regulating macrophage infiltration and polarization in AT, which resulted from the suppression of chemokine signaling pathways, including CCL2 and CXCR4." (PMID 35885044, 2022). "Markers of inflammation such as interleukin-1 beta (IL-1β), tumor necrosis alpha (TNF-α), monocyte chemoattractant protein-1 (MCP-1 or CCl-2), and interleukin 6 (IL-6), and markers related to obesity such as leptin and insulin were measured systemically in the blood." (PMID 36387539, 2022). "In addition, secretion of pro-inflammatory cytokines (TNF-α, IL-6, and CCL2) from macrophages and adipocytes is promoted in obesity, which is considered a form of chronic inflammatory disease." (PMID 34949748, 2022). "And computational analysis suggested that metformin may effectively dock with 1ALU, 5T1A residues in IL-6, CCL2 proteins in obesity and hypertension." (PMID 34334083, 2021). "CCL2 is known to be markedly increased in obesity, with roles in Mo recruitment." (PMID 34638514, 2021). "As noted by excellent systematic reviews, interactions between these cells occur through the secretion of obesity-associated hormones (e.g., leptin, adiponectin, and IGF1), cytokines (including chemokines) (e.g., TNF-α, IL-6, IL-8, IL-10, and CCL2/MCP-1), VEGF and other activated CAA mediators." (PMID 33557173, 2021). "Indeed, adipocytes secrete the primary ligand for C-C motif chemokine receptor 2 (CCR2; expressed on circulating monocytes), the monocyte chemoattractant CCL2 (MCP-1), and its expression increases in obesity." (PMID 34613819, 2021). "The second explanation is that CCL2 triggers resident AT macrophage proliferation during obesity." (PMID 33540898, 2021). "This example demonstrates that increased CCL2 may link obesity, AT inflammation, and fibrosis to certain types of cancers." (PMID 33540898, 2021). "Interestingly, miR-126, one of the top downregulated miRNAs in this study, has previously been related to the regulation of adipose tissue inflammation in human obesity, since it also targets CCL2, inhibiting its expression and release from adipose tissue." (PMID 33801145, 2021). "Despite that, CCL2 could represent one of the mechanistic links between obesity and related diseases which are at least in part mediated by a pro-inflammatory state." (PMID 33540898, 2021).
Obesity (continued). "Finally, we evaluated if the bacterial alterations found in CRC patients correlated with systemic inflammation, as evaluated by the circulating levels of the CCL2 cytokine marker previously found increased in several cancers and in obesity." (PMID 34639088, 2021). "Screening of obesity-associated proinflammatory cytokines and chemokines in subcutaneous white adipocytes demonstrated that BAFF, but not APRIL, upregulated the mRNA expression of multiple proinflammatory mediators, including Tnf, Cxcl1, Ccl2, and Ccl3." (PMID 34006859, 2021). "The effects CCL2 are multiple and include regulation of myeloid cell function, immune response, modulation of cell-killing properties of monocytes and macrophages, but also linking obesity to its related cardio-metabolic and malignant diseases." (PMID 33540898, 2021). "Despite the controversial effects of CCL2 in OC, the CCL2-CCR2 axis was recognized as a critical player in recruiting tumor-associated Mφ and facilitating the progression of cancer, indicating further promoting effects due to obesity." (PMID 34638514, 2021). "In our review, we focused on the role of CCL2 in the context of obesity-related diseases." (PMID 33540898, 2021). "All current in-silico findings might display the binding capability of metformin with IL-6, CCL2 proteins in obesity, and hypertension." (PMID 34334083, 2021). "CCL2 chemokines play an important role in the pathogenesis of a wide variety of disease processes including vascular permeability, attraction of immune cells during metastasis, neurological disorders, autoimmune diseases, obesity, and atherosclerosis." (PMID 34640602, 2021). "Moreover, various other fatty tissue products have been characterized, such as TNF-α, IL-6, IL-1, CCL2, and plasminogen activator inhibitor type-1, which play a crucial role in immune dysregulation in individuals with obesity." (PMID 34220807, 2021). "The obesity-induced elevation of CCL2 level further recruits macrophage in white adipose tissue." (PMID 33379163, 2020). "Moreover, the lncRNA MIR3142HG, recently described as important mediator of the inflammatory response in Idiopathic Pulmonary Lung Fibroblasts positively regulating CXCL8 and CCL2 release, is specifically up-modulated in obesity." (PMID 32714872, 2020). "Moreover, we observed that HED induced obesity in both WT and Ccl2-KO mice, but the latter showed higher testis/body weight ratio, testosterone level, and sperm density." (PMID 33148888, 2020). "Chemokine CCL2 is a mediator of macrophage accumulation in white adipose tissue in obesity." (PMID 33379163, 2020). "Obesity is associated with increased expression of adipokines including TNF-α, IL-6, and CCL2 which can cause damage to adipocytes and the release of FFAs, and the combined effect of TNF-α and FFAs may trigger further IL-8 production." (PMID 31443599, 2019). "CCL-2 is secreted mainly by adipocytes and macrophages during obesity." (PMID 31507583, 2019). "Interestingly, spontaneous (in the absence of stimulation) production of several chemokines (IL-8, CXCL10, Eotaxin, CCL4, and CCL2) was significantly reduced with pregravid obesity." (PMID 30131724, 2018). "Notably, increased adipose tissue levels of multiple β-chemokines (CCL2, CCL3, CCL5, CCL7, CCL8, CCL11) and chemokine receptors (CCR1, CCR2, CCR3, CCR5) have been linked with obesity and associated metabolic inflammation." (PMID 28396851, 2017). "However, previous reports in patients suggest that plasma CCL2 levels increase with obesity, potentially explaining the high basal levels found here, although the reason for the reduction in CCL2 after stoke in obese animals is unclear." (PMID 28798136, 2017). "Especially interesting and promising target molecules for obesity-derived implications in placenta could be CCL2, PRL, MMP12, TAC3, PRG2 and IGFBP1 that were the most dysregulated genes among our study group." (PMID 28125591, 2017). "CCL2/MCP-1 is a key driver of adipose tissue inflammation in obesity." (PMID 28608804, 2017).
Obesity (continued). "In contrast, obesity induces lipolysis and release of pro-inflammatory free fatty acids (FFAs) and factors such as C–C motif ligand 2 (CCL2) and TNF-α that recruit blood monocytes in adipose tissue, where they become polarized to the highly pro-inflammatory M1-like state." (PMID 28018292, 2016). "On the other hand, increased CCL2 in female adipose tissue could be indicative of a pro-inflammatory state, which is consistent with obesity-related adipose tissue inflammation." (PMID 27711160, 2016). "However, at the late stage of obesity, a significant increase of the donor-derived ATMs was found, accompanying with enhanced CCL2 level in the serum." (PMID 27031964, 2016). "MCP–1 (CCL2) in adipose tissue is reduced in NLRP3 deficient mice, suggesting that NLRP3 inflammasome plays a role in macrophage infiltration in adipose tissue and correlates with sustained levels of chronic inflammation in obesity." (PMID 26437377, 2015). "Adipocytes and infiltrating inflammatory cells (primarily macrophages) present within the tissue secrete key inflammatory proteins, such as TNF-a, IL-6, and CCL2/monocyte chemoattractant protein, and their gene expression and release are markedly increased in obesity." (PMID 25887648, 2015). "Genetic inactivation of CCL2 was demonstrated to not interfere with obesity-associated monocyte influx into WAT." (PMID 24741577, 2014). "There is a relationship between chronic inflammation and obesity, characterized by increased secretion of proinflammatory cytokines such as interleukin-(IL)-6, IL-8 and MCP-1/CCL2, abundant infiltration of activated macrophages into adipose tissue and obesity-induced insulin resistance." (PMID 21325706, 2011). "Expression of the chemokine CCL2, which hasbeen implicated in obesity-linked macrophage infiltration, was, however,not elevated in fat at this stage." (PMID 18584041, 2008). "We then hypothesized that leptin, highly elevated in patients with obesity and, in our studies, markedly correlated with higher CCL2/MCP‐1 expression in both plasma and vWAT, as well as in ASCs, increases the expression of this chemokine in ASCs by regulating H3K27 acetylation." (PMID 40518865, 2025). "Modulation of FSP27/CCL2 axis may be a novel therapeutic target for obesity-related AAA." (PMID 39872985, 2025). "The present study aimed to determine whether obesity-induced elevation in palmitic acid (PA), which is the most abundant of the free fatty acids (FFAs), increased CCL2 via the GPRs/KLF7 pathway in bone marrow adipocytes (BMA) to facilitate PCa growth and metastasis." (PMID 38221626, 2024). "It is worth noting that after retesting the CCR2 in these tumor tissues, we found that the expression levels of CCR2 in PCa tumor tissues also increased under obesity, which may be another positive response of tumor cells to search for CCL2 in distal bone marrow." (PMID 38221626, 2024). "In addition, it has been observed in obese individuals that obesity induced by a HFD triggers an increase in the production of chemokine (C-C motif) ligand 2/monocyte chemoattractant protein-1 (CCL2/MCP-1) within epithelial cells, ultimately leading to the development of a proinflammatory phenotype." (PMID 38138996, 2023). "This could also be related to the monocyte mobilization chemokine CCL2, which increases in obesity." (PMID 37569635, 2023). "Since obesity correlates with low grade inflammation and obese adipose tissue can be heavily infiltrated by immune cells, the mRNA levels of specific immune cell markers (Itgam and Il1b) and of tissue chemokines (Il6 and Ccl2) were quantified in pWAT, eWAT and iWAT." (PMID 36138030, 2022). "Nevertheless, deletion of CCL2 gene did not affect obesity-associated monocyte influx into WAT." (PMID 34948325, 2021). "Therefore, by regulating CCL2 expression, miR-347a-5p may modulate inflammation and alter lipid profile in obesity." (PMID 33801145, 2021).
Obesity (continued). "In addition, this miRNA may modulate the expression of CCL2, a pro-inflammatory biomarker found upstream in the pathway that leads to dyslipidaemia in obesity." (PMID 33801145, 2021). "Macrophages are recruited and activated by monocyte chemoattractant protein 1 (MCP1, also known as CCL2), secreted by adipocytes during obesity, and are necessary for tumour progression; accordingly, loss of MCP1 delays mammary tumourigenesis in a triple‐negative breast cancer model." (PMID 31930708, 2020). "To identify signals in fat tissue that might induce YAP/TAZ activation during obesity, we analyzed whether palmitic acid or several cytokines, including TNFα, interleukin (IL)-1β, CCL2, and IL-6 are able to induce YAP/TAZ target gene expression in 3T3-L1 adipocytes." (PMID 33116140, 2020). "Therefore, blockade of CCL2/CCR2 signaling by CCR2 depletion might ameliorate obesity-induced albuminuria through blocking oxidative stress, ER stress, and lipid accumulation." (PMID 31498850, 2019). "In addition to IL-6, we found CCL-2 was increased drastically in obesity EAE mice." (PMID 31507583, 2019). "In addition, the chemokine monocyte chemoattractant protein-1 (MCP-1/CCL2), and its receptor C-C motif chemokine receptor 2 (CCR2) play a critical role in macrophage infiltration and insulin resistance associated with obesity." (PMID 30723473, 2019). "However, whether the IL-17 axis impacts CCL2 expression in obesity-independent NAFLD remains unexamined." (PMID 26895034, 2016). "Obesity-induced increased levels of glucose and FFAs create stress in pancreatic islets, adipose tissue, liver, and muscle, resulting in increased local production and release of cytokines and chemokines such as IL-1β, TNFα, CCL2, CCL3, and CXC-chemokine ligand 8 (CXCL8, also known as IL-8)." (PMID 28018292, 2016). "Further characterization of its role in obesity-related comorbidities may open the door for more targeted interventions including more focused exercise programs, nutraceutical or pharmacological interventions that modulate CCL2 levels to tackle inflammation in obesity." (PMID 23557387, 2013). "Taken together, our findings indicate that in breast cancer patients, obesity enhances the activation of the FA/HIF‐1α/CCL2 axis in tumor tissues and the CCL2/CCR2/PPARα axis in adjacent adipose tissue." (PMID 41160815, 2026). "Taken together, these findings suggest that obesity‐induced lipid supply increases HIF‐1α expression in tumors, enhancing CCL2 secretion." (PMID 41160815, 2026). "Consistent with the literature, we observed significant hypertrophy in adipocytes from vWAT samples with obesity (Groups II and III) and an increase in LPS and inflammatory cytokines, including leptin and CCL2/MCP‐1." (PMID 40518865, 2025). "In brief, in obesity, adipose tissue secretes several chemokines, including MCP-1 (also known as CCL2) and CCL5, which can trigger signaling pathways and result in inflammatory reactions and insulin resistance." (PMID 41227378, 2025). "In the vWAT progenitor cells (ASCs), there was a substantial increase in CCL2 and an increase in the expression of KDM6A, as well as the acetylases CREBBP and EP300 in the patients with obesity." (PMID 40518865, 2025). "In an obesity model comprising rodents fed with ALA-rich flaxseed oil for 8 weeks, the CCL2 level was reduced, as well as adipocyte size and T-cell infiltration in adipose tissue." (PMID 40076892, 2025). "Other chemokines include but not limited to CCL2 (MCP-1), CCL3 (MIP-1α), CCL4 (MIP-1β), CCL19, CXCL1, CXCL8 or IL-8, CXCL10, and CXCL12 also play an important role in obesity and cancer immunotherapy." (PMID 40863244, 2025). "The chemokine ligand CCL2, also known as monocyte chemoattractant protein‐1 (MCP‐1), plays a crucial role by promoting the recruitment of monocytes that accumulate in WAT during obesity." (PMID 40518865, 2025). "In a diet-induced obesity (DIO) mouse model, researchers observed increased plasma concentrations of MCP-1/CCL2." (PMID 39769394, 2024).